IRS1 (insulin receptor substrate 1)
Diseases named in the same sentence as IRS1 in open-access papers (continued):
Sharing a sentence is not in itself a finding about the gene and the disease.
Insulin resistance (continued). "Taking all this into account, the cross-talk between FSH and insulin might involve IRS1, especially in case of insulin resistance, but this needs to be elucidated." (PMID 31174276, 2019). "An in vivo and in vitro study demonstrated that a high serum UA level could directly induce insulin resistance by inhibiting IRS1 and Akt insulin signaling." (PMID 30944567, 2019). "Interestingly we observed a progressive increase in the ratio of phospho-IRS1/Total IRS1 from 30 min to 4 h time period signifying insulin resistance." (PMID 31427921, 2019). "The current studies provide new insight into how different mechanisms of insulin resistance may be initiated by carrageenan or by high fat, and how several diverse mechanisms may be integrated at the level of IRS-1 phosphorylation." (PMID 31179345, 2019). "Risk alleles like FTO, ADIPOQ, INSR, IRS1, IRS2, PPARG, CAPN10 may leave individuals more vulnerable to insulin resistance and/or adiposity (which can result in peripheral insulin resistance), leading to high circulating insulin." (PMID 31367382, 2019). "Furthermore, qRT-PCR results indicated that VT influenced the expression of Irs1, Akt2, Mtor genes in the Akt signaling pathway, suggesting that VT enhanced insulin signaling and improved liver insulin resistance." (PMID 31096578, 2019). "Moreover, DYRK1A up-regulation of IRS-1 ameliorates insulin resistance induced by chronic high insulin exposure in SH-SY5Y cells and rat primary neurons." (PMID 31723029, 2019). "Furthermore, serine phosphorylation of insulin receptor substrate-1 (p-IRS-1(Ser307)) inhibits insulin signalling which contributes to peripheral insulin resistance." (PMID 31766382, 2019). "Impaired insulin signal transduction may be explained by a principal molecular mechanism, the serine phosphorylation of insulin receptor substrate 1 (IRS-1), which mediates insulin resistance through inhibitory effects on glucose transporter 4 (GLUT4)." (PMID 31485456, 2019). "For example, IRS-1 is an important element in insulin signaling pathway and disturbance of IRS1 complexes may lead to insulin resistance and T2DM, while the PPAR gamma is involved in the pathogenesis of various diseases including T2DM." (PMID 31775219, 2019). "Thus, the upregulated serine phosphorylation of IRS-1 plays a key role in the pathogenesis of insulin resistance." (PMID 30225267, 2018). "To investigate whether galangin can get insulin resistance better, we examined the phosphorylation state of ten proteins on the Akt/mTOR signal pathway, including IR, IRS1, PTEN, Akt, GSK3α, GSK3β, TSC2, mTOR, p70S6K, and RPS6." (PMID 30420897, 2018). "Ubiquitin D (UBD) expression is upregulated in the pathogenesis of diabetes, and UBD inhibits the activity of insulin receptor substrates 1 and 2 (IRS1 and IRS2), diminishing their ability to accept insulin, which leads to the downregulation of PI3KR1 expression and causes insulin resistance." (PMID 30131712, 2018). "Moreover, in cultured human endothelial cells, diosgenin has been found to ameliorate FFA-induced endothelial dysfunction and insulin resistance via inhibiting the IKKβ and IRS-1 pathways." (PMID 29534453, 2018). "Taken together, theaflavins at noncytotoxic doses could protect HepG2 cells against PA-induced insulin resistance by increasing glucose uptake and modulating the IRS-1/Akt/GLUT4 pathway." (PMID 30572687, 2018). "Our observation of an early reduction in IRS-1 expression in the second generation of recuperated animals in this study thus may be the first step towards the development of insulin resistance in this group." (PMID 29507362, 2018). "IRS1 expression levels in hepatocytes have been reported to be modulated also by miR-145; such miRNA was found upregulated in liver of mice treated with resistin, thus being involved in resistin-induced insulin resistance through IRS1 expression levels reduction." (PMID 30469501, 2018).
Insulin resistance (continued). "Modified Sanzi Yangqin Decoction relieves the insulin resistance by increasing IRS-1 phosphorylation at tyrosine in skeleton muscle of T2DM rats, which results from the increased level of p-IRS-1(Tyr895) protein and is related to the suppression of the PTP1B protein." (PMID 29721029, 2018). "Furthermore, silymarin can reduce steatosis and insulin resistance seen in NAFLD through restoration of the insulin receptor substrate-1 (IRS-1)/PI3K/Akt pathway." (PMID 30201879, 2018). "Serine phosphorylation of IRS-1 suppresses insulin signal transduction in a variety of cell backgrounds, which might contribute to peripheral insulin resistance." (PMID 30225267, 2018). "Accordingly, it has been demonstrated that TNF-α may induce insulin resistance by serine phosphorylation in IRS-1." (PMID 30134857, 2018). "Dysregulated phosphorylation of tyrosine and serine/threonine in IRS-1 may lead to the pathologic state of insulin resistance." (PMID 30419905, 2018). "The mechanism of how betaine enhances IRS-1 phosphorylation to improve insulin resistance remains unclear." (PMID 29881379, 2018). "Our findings suggest that up-regulation of miR-222 followed by reduction in IRS-1 expression may be a viable mechanism of insulin resistance in the liver." (PMID 29364977, 2018). "Pro-inflammatory cytokines, particularly TNF-α, could enhance the serine phosphorylation of insulin receptor substrate-1, which induced insulin resistance." (PMID 30453687, 2018). "Likewise, IRS-1 deficits have been shown to contribute to insulin resistance in animal models and diabetic patients." (PMID 29572520, 2018). "Impaired insulin signaling through IRS1 to Akt is often observed in insulin resistance and has been hypothesized to be upstream of defects in GLUT4 translocation." (PMID 29599292, 2018). "IRS-1 phosphorylation on serine 307 occurred because of protein kinase/c-Jun N-terminal kinase (SAPK/JNK) activation as the critical part for the molecular change that leads to insulin resistance." (PMID 30305144, 2018). "Only recently, curcumin was found to inhibit ER stress, to reduce insulin resistance through the inhibition of the JNK/insulin receptor substrate-1 (IRS-1) signalling, and to promote autophagy in endothelial cells exposed to palmitate, thus emphasizing its possible therapeutic outcome in ED." (PMID 29725497, 2018). "Then, it is reasonable to speculate that IL-13 plays a protective role in insulin resistance by promoting IRS-1 and AKT phosphorylation in insulin-dependent tissues via STAT3 and STAT6 activation as well as improvement of the beta-cell function." (PMID 29675435, 2018). "However, in insulin resistance, IR-B preferential activation by insulin results in IRS1/2-mediated increase in the activity of the p85α regulatory subunit of PI3K (PI3K p85α), which inhibits Akt thus reducing NO generation." (PMID 29104874, 2017). "In addition, chronic insulin resistance induces IRS1 phosphorylation at Ser307 and its partial degradation." (PMID 28505155, 2017). "An analysis of the insulin signaling pathway, including glycolysis and gluconeogenesis, showed that a high dietary arginine level (2.70%) resulted in the upregulation of S6K1 and inhibition of IRS-1, PI3K and Akt mRNA levels, which caused insulin resistance and elevated plasma glucose content." (PMID 28801592, 2017). "Indeed, IL-1β induces insulin resistance by decreasing IRS-1 protein and inhibiting insulin-induced PKB phosphorylation." (PMID 28765650, 2017). "Moreover, this activation can cause hepatic insulin resistance through activation of the c-Jun N-terminal kinase (JNK) pathway, which inhibits insulin signaling through inactivation and/or degradation of IRS-1." (PMID 28587303, 2017). "Interestingly, AD has insulin and IGF-1 resistance with dysfunctional IRS-1 mediated insulin resistance." (PMID 28505155, 2017).
Insulin resistance (continued). "Amino acid signaling may facilitate insulin resistance, by activation of the mammalian target of rapamycin (mTOR), a nutrient sensor that operates a detrimental feedback loop toward insulin receptor substrate 1 signaling." (PMID 28878172, 2017). "This indicated that IRS1 and IRS2 were related to HCV-associated insulin resistance." (PMID 29285303, 2017). "The process of insulin resistance is associated with defects in insulin signalling downstream of insulin receptor (INSR), insulin Receptor Substrate 1/2 (IRS-1/2), Phosphoinositide 3-Kinase (PI3K)/AKT Serine/Threonine Kinase (AKT) and Glucose Transporter 4 (GLUT4)." (PMID 29050364, 2017). "Insulin resistance in these pathological conditions results from reduced Akt activation mainly due to inhibition of IRS1/2, likely due to the increased activity of the mammalian target of rapamycin (mTOR) resulting from lower activity of adenosine monophosphate kinase." (PMID 29104874, 2017). "The IL-1β inhibit IRS-1 signaling to promote insulin resistance." (PMID 28166749, 2017). "Increased serine phosphorylation of IRS1 could provide a novel mechanism to explain the insulin resistance reported in bGH mice and could play a role in inhibiting excess IGF-1 signaling in the gastrocnemius." (PMID 28870245, 2017). "Insulin resistance could also decrease the AMPK phosphorylation and increase the expression levels of SREBP-1c, which further suppressed IRS-1 activation, inhibits IRS-1-associated insulin signaling and thereby decreases glucose uptake and utilization." (PMID 28867797, 2017). "IRS-1 is activated by insulin via tyrosine phosphorylation of IRS-1 in the normal signaling pathway, but the Ser307 phosphorylation of IRS decreases its ability to phosphorylate tyrosine and can therefore cause insulin resistance." (PMID 28607631, 2017). "Reduced expression of Irs1 in OB dams could lead to insulin resistance in placental labyrinth and affect these processes." (PMID 26925174, 2016). "Thus, blocking insulin resistance by inhibiting IRS1 phosphorylation likely will require the inhibition of multiple enzymes." (PMID 26956053, 2016). "To fit the data obtained in db/db medium, we hypothesized that insulin resistance also increases because of an increased IRS1 degradation due to enhancement of mTORC2 signaling." (PMID 27149630, 2016). "Studies have focused on the IRS1/pAKT pathway, similar to peripheral insulin resistance." (PMID 27676071, 2016). "Furthermore, a hyperuricemia mice model showed increased phospho-IRS1 (Ser307) and inhibited phospho-Akt levels with glucose intolerance and insulin resistance." (PMID 26836389, 2016). "The results of IRS-1−/− mice fed an SL or SO in this study showed no significant changes in the metabolic phenotypes or β cell mass, indicating that insulin resistance was not the cause of β cell failure." (PMID 26937254, 2016). "Notably, activation of nAChR leads to insulin resistance by increasing insulin receptor substrate-1 (Ser636) phosphorylation." (PMID 27666821, 2016). "Increased Ser phosphorylation of IRS-1 is a common finding in insulin resistance." (PMID 26836389, 2016). "Insulin resistance, chronic inflammation, oxidative damage, and dyslipidemia are generally characterized by the activation of the IRS1/PI3K/AKT pathway, particularly, this being the route activated by insulin or insulin-like growth factor 1 (IGF-1) in insulin resistance." (PMID 26999118, 2016). "In muscle, insulin resistance seems to attenuate predominantly IRS1-dependent GLUT4 translocation and glucose uptake, though some reports suggest that IRS2-dependent insulin signaling cascade could also be involved in glucose metabolism in myocytes." (PMID 27247938, 2016). "They found that the risk loci could be subdivided into five clusters including one cluster with four loci, PPARγ, KLF14, IRS1 and GCKR, associated with insulin resistance." (PMID 27312935, 2016).
Insulin resistance (continued). "Therefore, the upregulation of miR-96 provokes an impairment of insulin signaling and glycogen synthesis in hepatocytes through the repression of INSR and IRS-1, and that miR-96 is a causal factor for SFA-induced hepatic insulin resistance." (PMID 28036389, 2016). "Likewise, 1,25(OH)2D treatment in C2C12 cells rescues diet-induced insulin resistance via decreased IRS-1 serine phosphorylation and increased IRS-1 tyrosine and protein kinase-B (Akt) serine phosphorylation." (PMID 27754361, 2016). "IL-6 is one of the most studied inflammatory cytokine, which modulates insulin resistance via numerous mechanisms such as the c-Jun N-terminal kinase 1 (JNK1)-mediated serine phosphorylation of IRS1, with elevated circulating IL-6 levels observed in insulin-resistant subjects." (PMID 26842399, 2016). "Phosphorylation of IRS1 (Ser307) is a representative molecular marker of insulin resistance." (PMID 26836389, 2016). "Phosphorylation of IRS1 at Ser307 is of interest because it has been implicated as a causative mechanism of insulin resistance, as part of negative or positive control signals." (PMID 26836389, 2016). "Notably, JNK is recognised as a major contributor to insulin resistance as it induces the phosphorylation of insulin receptor substrate 1 (IRS1) at Ser307." (PMID 27243589, 2016). "We also assessed the effects of DPP-4 inhibition in IRS-1 deficient mice fed an SL or SO diet as a model of insulin resistance without obesity." (PMID 26937254, 2016). "We did not replicate associations with several well-known T2DM genes, including TCF7L2, FTO, IRS1, and KCNQ1, in our Han Chinese population (In our data set, the FTO gene SNPs yielded some associations with insulin resistance related phenotypes in quantitative analyses." (PMID 26139146, 2015). "IRS-1 plays a crucial role in determining insulin resistance." (PMID 25912041, 2015). "GRK2 thus plays a role in chronic ET-1 induced insulin resistance by inhibiting IRS-1." (PMID 26474286, 2015). "As the important target of the inflammatory pathways, NF-κB could disrupt IRS1 and downregulate the expression of IRS1 under conditions of insulin resistance." (PMID 26843885, 2015). "Given that enhanced activation of JNK and NF-κB pathways may induce insulin resistance via phosphorylation of insulin receptor substrate-1 (IRS-1) on serine 307 and dephosphorylation of Akt31, we examined the effects of WEGL on insulin activity." (PMID 26102296, 2015). "In addition to TNFα actions on IRS-1, TNFα also can activate other proteins known to be involved in insulin resistance, namely suppressor of cytokine signaling 3 (SOCS3)." (PMID 25874611, 2015). "Hilder and colleagues found that elevated activity of c-Jun NH2-terminal kinase (JNK) phosphorylated IRS-1 at Ser307 and further reduced Akt activity, providing biochemical evidence for the development of insulin resistance in 2-week to 13-week unloaded soleus muscle." (PMID 25713812, 2015). "Moreover, doxorubicin can decrease expression of genes (IRS1, Glut4, AMPK, and GSK3b) involved in insulin signaling in muscle tissues and thus can cause systemic insulin resistance, thus leading to the development of type 2 diabetes-like condition." (PMID 26089893, 2015). "When insulin levels remain elevated for a long period of time, the phosphorylation of serine in IRS1 may trigger insulin resistance in cells." (PMID 26084330, 2015). "It is possible, therefore, that S-nitrosylation of IRS-1 may work in concert with S-nitrosylation of Akt to the insulin resistance in sedentary OLETF rats." (PMID 26172834, 2015). "An IRS-1 Ser 307 mutation was shown to protect against tumor necrosis factor alpha induced inhibition of IRS-1 tyrosine (Tyr) phosphorylation via the JNK kinase pathway; thus, Ser 307 phosphorylation is frequently cited as a cause of stress-induced insulin resistance." (PMID 25978724, 2015).
Insulin resistance (continued). "Our studies showed that insulin resistance induced by sodium oleate could lead to overexpression of NF-κB protein and that IRS1 and GLUT4 proteins were impaired." (PMID 26843885, 2015). "It was found in the animal experiments that ECD could reduce blood glucose, regulate lipid metabolism, and reduce the expression of IR, IRS-1, and Cav-1, so as to improve insulin resistance." (PMID 26504476, 2015). "In addition, BC ameliorated insulin resistance by decreasing insulin release, improving glucose tolerance, and restoring insulin signaling by recovering IRS-1 expression in skeletal muscle tissue." (PMID 26504474, 2015). "Although previous evidence showed that OA attenuated insulin resistance in part through inhibiting inflammation and enhancing the IRS-1 signal, the role of NF-κB in attenuating insulin resistance by OA remains essentially unknown." (PMID 26843885, 2015). "Report showed that PP4C could interact with IRS-4 and down-regulate IRS-411, we wondered whether PP4 was involved in TNF-α-induced insulin resistance by interacting with IRS-1." (PMID 26666849, 2015). "In addition, increased levels of TNFα and SOCS3 lead to enhanced IRS-1 phosphorylation on serine 307, elevated IR (Tyr960), and decreased phosphorylation of IR (Tyr1150/1151), leading to insulin resistance and increased apoptosis." (PMID 25888955, 2015). "In addition, hyperphosphorylation of serine at residues Ser302, Ser307, Ser612, and Ser632 in IRS1 was suggested to be responsible for increased insulin resistance in animal models." (PMID 26257839, 2015). "In the HUVECs, PA attenuated the insulin-mediated tyrosine phosphorylation of IRS-1 and consequently reduced glucose uptake, suggesting that PA may induce insulin resistance." (PMID 25815690, 2015). "For example, PKCθ and -ε induce insulin resistance by inhibiting insulin receptor substrate 1 (IRS1) and the insulin pathway, while PKCδ and -λ have the opposite effect and stimulate the insulin pathway by activating IRS1." (PMID 26298773, 2015). "The results shown that the it was mild to moderate impaired the ability of phosphorylated IRS-1 bind to the p85 regulatory subunit of PI 3-K by the variants, and the functional defect of IRS-1 variants play a contributory role in insulin resistance and diabetes susceptibility." (PMID 25978640, 2015). "Acute inhibition of IRS-1 in rats also leads to insulin resistance." (PMID 24749062, 2014). "Notably, the enhanced liver IRS1 activation concomitant with increased blood glucose in ME1-Tg mice suggests the onset/development of systemic insulin resistance." (PMID 25402228, 2014). "Overall, our findings convincingly demonstrate that PPARG Pro12Ala –IRS1 Gly972Arg interactions, PPARG Pro12 and susceptibility to environmental factors might modulate the relationship between insulin resistance and type 2 diabetes in this population." (PMID 24447396, 2014). "Ser302 in rat/mouse IRS-1 (corresponding to Ser307 of human IRS-1) is one of the molecular mechanisms proposed as an indicator of cellular energy status underpinning the development of insulin resistance." (PMID 25309812, 2014). "Another potential site of IRS‐1 serine phosphorylation that could mediate insulin resistance was at Ser1101." (PMID 25472611, 2014). "Either IRS-1 or IRS-2 gene deletion in mice leads to insulin resistance." (PMID 25580119, 2014). "However, in the absence of protein data, it is difficult to fully appreciate the physiological impact of salt‐induced increases in IRS‐1 and it is likely that any potential mechanisms pertaining to insulin resistance reside downstream of IRS‐1 signaling." (PMID 25096554, 2014). "Furthermore, serine phosphorylation of IRS1, a marker of insulin resistance, was increased under lipotoxicity." (PMID 24936385, 2014). "In addition, JNK-dependent serine phosphorylation of insulin receptor substrate-1 (IRS-1) is a key link between ER-stress and insulin resistance." (PMID 24896641, 2014).